HTR2B (5-hydroxytryptamine receptor 2B)
Description:
G protein-coupled receptor for 5-hydroxytryptamine (serotonin). Also functions as a receptor for various ergot alkaloid derivatives and psychoactive substances. Ligand binding causes a conformation change that triggers signaling via guanine nucleotide-binding proteins (G proteins) and modulates the activity of downstream effectors. HTR2B is coupled to G(q)/G(11) G alpha proteins and activates phospholipase C-beta, releasing diacylglycerol (DAG) and inositol 1,4,5-trisphosphate (IP3) second messengers that modulate the activity of phosphatidylinositol 3-kinase and promote the release of Ca(2+) ions from intracellular stores, respectively. Beta-arrestin family members inhibit signaling via G proteins and mediate activation of alternative signaling pathways. Plays a role in the regulation of dopamine and 5-hydroxytryptamine release, 5-hydroxytryptamine uptake and in the regulation of extracellular dopamine and 5-hydroxytryptamine levels, and thereby affects neural activity. May play a role in the perception of pain (By similarity). Plays a role in the regulation of behavior, including impulsive behavior. Required for normal proliferation of embryonic cardiac myocytes and normal heart development (By similarity). Protects cardiomyocytes against apoptosis (By similarity). Plays a role in the adaptation of pulmonary arteries to chronic hypoxia (By similarity). Plays a role in vasoconstriction (By similarity). Required for normal osteoblast function and proliferation, and for maintaining normal bone density (By similarity). Required for normal proliferation of the interstitial cells of Cajal in the intestine (By similarity).
Synonyms: 5-HT-2B; 5-HT2B; 5-HT(2B)
Tractability: Small molecule: an approved drug acts on it; a structure with a bound ligand is known; a high-quality ligand is known; it belongs to a druggable protein family. Antibody: UniProt places it where antibodies can reach, with high confidence; its Gene Ontology location is reachable by antibodies, with high confidence; UniProt predicts a signal peptide or a membrane-spanning region. PROTAC: ubiquitination databases record sites on it; a small molecule that binds it is known.
Target class: Monoamine receptor; Family A G protein-coupled receptor; Small molecule receptor (family A GPCR); Serotonin receptor; Membrane receptor
Chemical probes: NBOH-2C-CN (high quality)
Safety:
Unwanted effects reported when the protein is acted on. In parentheses: how it was acted on, where the effect was seen, and who reports it.
cardiac valvulopathy (Lynch et al. (2017): activation, acute dosing, nervous system, cardiovascular, gastrointestinal; Urban et al. (2012): activation, cardiovascular system)
pulmonary hypertension (Bowes et al. (2012): activation, cardiovascular system, development, pulmonary; Lynch et al. (2017): activation, acute dosing, nervous system, cardiovascular, gastrointestinal)
cardiac development effect leading to cardiomyopathy (based on knockout mouse data) (inhibition, developmental toxicity; cardiovascular system; source: Urban et al. (2012))
cardiovascular malformations (inhibition, developmental toxicity; nervous system, cardiovascular, gastrointestinal; source: Lynch et al. (2017))
decreased anxiety (activation, acute dosing; nervous system, cardiovascular, gastrointestinal; source: Lynch et al. (2017))
decreased gastrointestinal transit (inhibition, acute dosing; nervous system, cardiovascular, gastrointestinal; source: Lynch et al. (2017))
decreased pain (inhibition, acute dosing; nervous system, cardiovascular, gastrointestinal; source: Lynch et al. (2017))
hypertension (activation; cardiovascular system; source: Urban et al. (2012))
increased pain (activation, acute dosing; nervous system, cardiovascular, gastrointestinal; source: Lynch et al. (2017))
possible cardiac effects, especially during embryonic development (inhibition, developmental toxicity; cardiovascular system, development, pulmonary; source: Bowes et al. (2012))
potential cardiac valvulopathy (activation; cardiovascular system, development, pulmonary; source: Bowes et al. (2012))
Gene: Protein-coding gene on chromosome 2 (231,108,230 to 231,125,080, reverse strand). Ensembl gene ENSG00000135914.
Subcellular location: Cell membrane; Synapse, synaptosome
Subcellular location (Human Protein Atlas): Nucleoplasm
Pathways (Reactome):
Signal Transduction: G alpha (q) signalling events; Serotonin receptors
Gene Ontology:
Molecular function: G protein-coupled serotonin receptor activity; G-protein alpha-subunit binding; Gq/11-coupled serotonin receptor activity; protein binding; serotonin binding; GTPase activator activity; neurotransmitter receptor activity; G protein-coupled receptor activity
Biological process: calcium-mediated signaling; ERK1 and ERK2 cascade; G protein-coupled receptor signaling pathway; G protein-coupled serotonin receptor signaling pathway; intestine smooth muscle contraction; intracellular calcium ion homeostasis; phospholipase C-activating serotonin receptor signaling pathway; positive regulation of canonical NF-kappaB signal transduction; positive regulation of cell population proliferation; positive regulation of cytokine production; positive regulation of endothelial cell proliferation; positive regulation of ERK1 and ERK2 cascade; positive regulation of phosphatidylinositol biosynthetic process; regulation of behavior; release of sequestered calcium ion into cytosol; response to xenobiotic stimulus; vasoconstriction; cardiac muscle hypertrophy; chemical synaptic transmission; embryonic morphogenesis; G protein-coupled receptor signaling pathway, coupled to cyclic nucleotide second messenger; heart morphogenesis; negative regulation of apoptotic process; neural crest cell differentiation; neural crest cell migration; and 4 more
Cellular component: cytoplasm; G protein-coupled serotonin receptor complex; nucleoplasm; plasma membrane; dendrite; membrane; synapse
Genetic constraint (gnomAD): Loss-of-function variants: 31 observed, 41.69 expected, observed/expected ratio (o/e) 0.74, 90% interval 0.56 to 1. The upper end of that interval is the gene's LOEUF score, 1, which puts it in group 4 of 6, group 1 being the genes least tolerant of losing a copy. Missense variants: 562 observed, 611.09 expected, observed/expected ratio (o/e) 0.92, 90% interval 0.86 to 0.99. Synonymous variants: 210 observed, 218.79 expected, observed/expected ratio (o/e) 0.96, 90% interval 0.86 to 1.08.
Homologues: Orthologues: chimpanzee HTR2B (99% identical), macaque HTR2B (98% identical), pig HTR2B (91% identical), guinea pig HTR2B (89% identical), rabbit HTR2B (89% identical), dog HTR2B (86% identical), mouse Htr2b (83% identical), rat Htr2b (82% identical), tropical clawed frog htr2b (63% identical), zebrafish htr2b (56% identical), Drosophila melanogaster 5-HT2A (31% identical), Caenorhabditis elegans ser-6 (16% identical). Paralogues in human: HTR2A (42% identical), HTR2C (40% identical), HTR7 (22% identical), HTR1B (22% identical), HTR1E (22% identical), HTR6 (21% identical), HTR1F (20% identical), HTR5A (20% identical).
Diseases named in the same sentence as HTR2B in open-access papers:
HTR2B is named in the same sentence as 115 diseases in open-access papers, as found by Europe PMC text mining. Sharing a sentence is not in itself a finding about the gene and the disease. The quoted sentences say what the papers report.
Anxiety (12 papers, 2016 to 2025). Intense feelings of nervousness, tension, or panic often arise in response to interpersonal stresses. "First, we show that in our anxiety-related behavioral data and gene expression results for Htr2b, a gene implicated in these behaviors, we can find sex differences only if we account for the estrous cycle stage." (PMID 36307876, 2022). "We further looked into our molecular data, including ventral hippocampal gene expression of two genes: Ptprt, (encoding protein tyrosine phosphatase receptor type T), involved in the development of dendrite spines; and Htr2b (encoding serotonin receptor 2b), important for anxiety-related behavior." (PMID 36307876, 2022). "For example, 5-HT1A knockout resulted in an anxiety phenotype and abnormal gene expression of HTR2B was found to be a marker of uveal melanoma." (PMID 37795441, 2023). "With Htr2b expression, we see the pattern that we observed with anxiety-related behavior; males and females show similar variability and sex difference can only be detected when there is information about the estrous cycle stage." (PMID 36307876, 2022). "HTR1A, HTR1B, HTR2A, and HTR2B were commonly targeted in preclinical studies for the anxiety treatment as well as the anxiolytic-like studies of SZJ." (PMID 33178009, 2020). "As candidate genes, this study selected three serotonin (5-HT) receptor genes htr1Aa, htr1B, and htr2B, as well as the two 5-HT transporter genes slc6a4a and slc6a4b for their involvement in the regulation of the serotonergic system and in anxiety related behaviors." (PMID 32275662, 2020). "The lack of a relationship at slc6a4b and htr2B mRNA transcript with bottom-dwelling might suggest that these genes are not as strongly associated with anxiety." (PMID 32275662, 2020). "Using TargetScan 6.2 and Diana microT-CDS, in silico prediction yielded high scores for 3’UTR binding of hsa-miR-579-3p for GLRB, HTR2B, and NPY5R, in line with regulation of possible anxiety candidate genes." (PMID 30341278, 2018).
uveal melanoma (11 papers, 2014 to 2024). A melanoma derived from melanocytes of the uveal tract. "HTR2B was recently described as being a suppressor gene whose mutations are related to the prognosis of squamous lung cancer and metastasis in uveal melanoma." (PMID 38093305, 2023). "HTR2B gene has been described as an oncogene in uveal melanoma, among other solid tumors, and as a tumor suppressor gene in ovarian cancers." (PMID 38093305, 2023). "We then examined the correlation of altered HTR2B expression on progression-free survival in primary uveal melanomas from the TCGA database and found that patients with increased HTR2B expression correlated with development of metastasis (n = 79, p = 0.005)." (PMID 36230539, 2022). "CHCs (gp100+,HTR2B+/CD45+/ CD25−/CD203c−) were readily identified in all uveal melanoma patients’ peripheral blood specimens, while CTCs (gp100+,HTR2B+/CD45−/CD25−/CD203c−) were found in only a subset." (PMID 36230539, 2022). "The results of this study therefore demonstrate that members from the STAT family of TFs positively contribute to the expression of HTR2B in uveal melanoma." (PMID 35163491, 2022). "We then re-analyzed a subset of uveal melanoma patients across all stages of disease using a cocktail of antibodies (gp100, HTR2B, CD45, CD25, CD203c) for CHC and CTC detection." (PMID 36230539, 2022). "The rest of the genes above were also over-expressed metastatic cancers originating from breast cancer (ABCC5), kidney renal clear carcinoma (LRFN1), hepatocellular carcinoma (ELOVL6), and uveal melanoma (HTR2B)." (PMID 34680307, 2021). "The results of this study will help understand better the molecular mechanisms accounting for the abnormal expression of the HTR2B gene in uveal melanoma." (PMID 30347896, 2018). "Interestingly, expression profiling using a 12‐gene assay reliably distinguished metastasising from non‐metastasising uveal melanomas in humans and four of these genes (HTR2B, FXR1, LTA4H, and CDH1) are overexpressed in metastasising canine uveal melanoma." (PMID 32652526, 2020). "Several genes, such as HTR2B, CHL1, the ZNF family, YWHAZ and FYN provide potential candidates for distinguishing between uveal melanoma whether contain liver metastases in the future." (PMID 24597767, 2014). "However, the apparent lack of functionality for both of these STAT distant sites might be context-dependent and a more in-depth characterization will be required before one can assume that neither are contributing to hTR2B gene expression in uveal melanoma." (PMID 35163491, 2022).
pulmonary hypertension (8 papers, 2015 to 2026). Increased pressure within the pulmonary circulation due to lung or heart disorder. "In addition, it plays a role in the development of pulmonary hypertension depending on the expression of 5-hydroxytryptamine receptor 2B (HTR2B) in bone marrow progenitor cells." (PMID 34568491, 2021).
colitis (7 papers, 2008 to 2025). Inflammation of the colon. "In addition, knockout of the htr2b gene which encodes the 5-HT2B receptor demonstrated 5-HT2B prevents the development of colitis, suggesting the activation of the 5-HT2B receptor could help prevent IBD." (PMID 38137946, 2023). "Indole treatment reduced LBP production and M1 macrophage polarization both in mice with DSS-induced colitis and in lipopolysaccharide-treated mouse macrophages; however, the HTR2B antagonist reversed the effects of indole." (PMID 39180723, 2024). "Mice with a tissue-specific KO of HTR2B in the intestine are more vulnerable to dextran sodium sulfate (DSS)-induced colitis." (PMID 39180723, 2024). "The reduction of LBP and the activation of HTR2B via indole reduce M1 macrophage polarization during colonic inflammation." (PMID 39180723, 2024). "We treated AOM/DSS colitis model C57BL/6 mice with the 5-HT2B antagonists SB-204741 and Compound-15 and found that the changes in body weight corresponded to those observed with the Htr2bΔIEC colitis mouse model." (PMID 35664068, 2022). "However, the KO of HTR2B in the intestinal epithelial cells of mice aggravates the severity of AOM/DSS-induced colitis by inhibiting TGF-β/SMAD signaling and activating IL-6/STAT3 signaling." (PMID 39180723, 2024). "Transcriptomic analysis showed that HTR2B agonist administration strengthened the beneficial effects of Trp in DSS-induced colitis mice with antibiotic exposure by reducing gut lipopolysaccharide-binding protein (LBP) production, IκB-α/nuclear factor-κB signaling, and M1 macrophage polarization." (PMID 39180723, 2024). "In addition, knockout of the Htr2b gene, which encodes the 5-HT2B receptor, induces colitis and promotes colitis-associated cancer." (PMID 37623246, 2023). "To investigate the role of 5-HT2B in the inflammation of CAC, we induced acute colitis by administering 3% DSS in the drinking water for the Htr2bΔIEC and WT mice for 5 days beginning on day 5 after AOM injection." (PMID 35664068, 2022). "We combined the use of an HTR2B agonist (BW723C86) and an HTR4 antagonist (GR113808) to elucidate the mechanism by which HTRs affect the immunoregulatory effects of Trp in mice with Abx pre-exposure and DSS-induced colitis." (PMID 39180723, 2024).
depression (6 papers, 2012 to 2021). "Our study indicates that four genes related to neuropathic syndrome, stress, anxiety disorders and depression (Acvr1c, Cort, Htr2b and Pnoc) may have impaired response to stroke in aged rats." (PMID 23251410, 2012).
breast carcinoma (5 papers, 2021 to 2025). "To explore the potential mechanisms of HTR2A and HTR2B as prognostic biomarkers for breast cancer, we analyzed the association between these two HTR receptors and immune cell infiltration in the tumor microenvironment through the TIMER database." (PMID 37795441, 2023). "The expression levels of HTR1A, HTR1B, HTR2A, HTR2B, HTR2C, HTR4, and HTR7 were significantly downregulated in highly malignant breast cancer types." (PMID 37795441, 2023). "However, when compared to normal breast tissue, HTR1A, HTR1B, HTR2A, HTR2B, HTR2C, HTR4, and HTR7 were suppressed in high malignancy breast cancer types, whereas they were highly expressed in low malignant breast cancer." (PMID 37795441, 2023). "Therefore, it was hypothesized that low expression of HTR2A and HTR2B inhibits the activation of CD8+ T cells, and subsequently promotes breast cancer invasion and leads to poor prognosis of breast cancer patients." (PMID 37795441, 2023). "In contrast, the expression patterns of SNX, HTR2B, RGS4, and LYN were not homogeneous and differed among the breast cancer subtypes." (PMID 39267843, 2024).
gastric cancer (5 papers, 2021 to 2025). A primary or metastatic malignant neoplasm involving the stomach. "Research has identified serotonin receptors, specifically HTR2A, HTR2B, HTR3A, and HTR7, as potential targets for both the prevention and treatment of stomach cancer." (PMID 39766808, 2024).
myocardial hypertrophy (5 papers, 2011 to 2022). "Therefore, for cardiomyopathy caused by hypertension, reducing the expression of HTR2B may provide a new approach to treatment of myocardial hypertrophy and consequent avoidance of this cause of heart failure." (PMID 37551283, 2022). "Serotonin (5-hydroxytryptamine) receptors subtype 2B (HTR2B) play an essential role in cardiac function and development, and their overexpression in rats leads to myocardial hypertrophy." (PMID 37551283, 2022). "In the present study, we found IL-18 upregulated HTR2B and played a critical role in myocardial hypertrophy." (PMID 37551283, 2022). "In the hearts of rats, overexpression of HTR2B induces mitochondrial hyperplasia, leading to myocardial hypertrophy." (PMID 37551283, 2022). "A new approach to treatment of myocardial hypertrophy and avoidance of consequent heart failure by targeting HTR2B seems plausible." (PMID 37551283, 2022). "KEGG pathway enrichment analysis showed that the CXCR4 and HTR2B were enriched in calcium signaling pathway, which had been extensively characterized in the role in cardiac hypertrophy and remodeling processes." (PMID 32682418, 2020). "However, like the relationship between IL-18 signaling and cardiac hypertrophy, the role of HTR2B in cardiomyocyte hypertrophy remains to be fully elucidated." (PMID 37551283, 2022). "Manipulating HTR2B may provide a new approach to treatment of myocardial hypertrophy or heart failure." (PMID 37551283, 2022). "Therefore, HTR2B might play an important key role in the process of IL-18-induced myocardial hypertrophy." (PMID 37551283, 2022). "Previous studies have found that 5-hydroxytryptamine receptor 2B (HTR2B) can be enriched in the calcium signaling pathway, which plays a key role in the processes of myocardial hypertrophy and remodeling." (PMID 35966550, 2022).
valvular heart disease (5 papers, 2016 to 2026). "However, new clinical and pharmacological evidence have raised concern about their potential association with valvular heart disease (VHD), which may be mediated by inhibition of the serotonin transporter (SERT) and activation of the 5-hydroxytryptamine receptor 2B (5-HT2B receptor)." (PMID 41694885, 2026).